TRAK1 (trafficking kinesin protein 1)
Diseases named in the same sentence as TRAK1 in open-access papers:
TRAK1 is named in the same sentence as 34 diseases in open-access papers, as found by Europe PMC text mining. Sharing a sentence is not in itself a finding about the gene and the disease. The quoted sentences say what the papers report.
colorectal cancer (4 papers, 2011 to 2020). A primary or metastatic malignant neoplasm that affects the colon or rectum. "TRAK1 has been shown to be a promising diagnostic marker for gastric cancer and a prognostic marker in colorectal cancer." (PMID 28388658, 2017). "Additionally, altered Trak1 protein expression is associated with gastric and colorectal cancers and recently, whole exome sequencing has identified pathogenic variants in Trak1 that cause human fatal encephalopathy." (PMID 28924745, 2018). "Whether TRAK1 plays a different role in bladder cancer progression compared to gastric and colorectal cancer should be further studied." (PMID 28388658, 2017).
Epileptic encephalopathy (4 papers, 2021 to 2025). A condition in which epileptiform abnormalities are believed to contribute to the progressive disturbance in cerebral function. "Another DMR overlapped TRAK1 associated with autosomal recessive developmental and epileptic encephalopathy." (PMID 40044822, 2025). "TRAK1 is involved in mitochondrial trafficking, and bi-allelic loss-of-function variants in TRAK1 are associated with developmental and epileptic encephalopathy (OMIM #618201)." (PMID 34663447, 2021). "Moreover, mutations in the motor adaptor TRAK1 are linked to epileptic encephalopathy early infantile 68; in TRAK1-deficient patient fibroblasts, the mitochondria are irregularly distributed and have reduced motility, decreased membrane potential and a lower respiratory capacity." (PMID 33912943, 2021). "Another DMR overlapped TRAK1 (OMIM *608112), which is associated with autosomal recessive developmental and epileptic encephalopathy." (PMID 40044822, 2025). "TRAK1 deficiency (TRAK1, autosomal recessive inheritance, MIM #608112) in humans has been associated with developmental delay and epileptic encephalopathy, whereas TRAK2 has not been correlated with a disease yet." (PMID 38872485, 2025).
Hypertonia (3 papers, 2009 to 2018). A condition in which there is increased muscle tone so that arms or legs, for example, are stiff and difficult to move. "Genetic studies have identified a homozygous truncation mutation in Trak1 that causes hypertonia in mice." (PMID 28924745, 2018). "In agreement with our finding of hypertonia mutation-induced partial mislocalization of Trak1 from mitochondria to the cytosol, super-resolution imaging analysis showed presence of Trak1 hyrt in both the OMM and cytosol." (PMID 28924745, 2018). "We found that hypertonia-associated mutation impairs Trak1 mitochondrial localization and its ability to facilitate mitochondrial tethering and fusion." (PMID 28924745, 2018). "A frameshift mutation in the Trak1 gene that generates a C-terminal truncated form of Trak1 has been identified as the genetic defect for causing recessively transmitted hypertonia in mice." (PMID 28924745, 2018). "A homozygous frameshift mutation in the mouse Trak1 gene, which produces a truncated protein, was found to cause a recessively transmitted form of hypertonia, a neurological dysfunction characterised by postural abnormalities, jerky movements, and tremor." (PMID 19837565, 2009). "We found that the percentage of Trak1 hyrt mutant associated with the mitochondrial fraction was significantly decreased compared to that of Trak1 WT or endogenous Trak1, providing additional evidence for hypertonia mutation-induced impairment in Trak1 mitochondrial localization." (PMID 28924745, 2018). "We found that the ability of exogenous Trak1 to induce mitochondrial hyperfusion was significantly reduced by hypertonia-linked mutation, as only 59.5% ± 8.6% of Trak1 hyrt-expressing cells had hyperfused mitochondria, with predominately elongated mitochondria rather than enlarged mitochondria." (PMID 28924745, 2018). "Furthermore, our finding of impairment of Trak1-mediated mitochondrial fusion by hypertonia-associated mutation provides new insights into the pathogenic mechanism of hypertonia." (PMID 28924745, 2018). "Genetic analyses have identified a homozygous Trak1 mutation resulting in a C-terminal truncated form of Trak1 as the cause of recessively inherited hypertonia, but the pathogenic mechanism of Trak1 mutation remains unknown." (PMID 28924745, 2018). "Quantitative analysis showed that Trak1 hyrt mutant had significantly reduced colocalization with the mitochondrial marker TOM20 than that of Trak1 WT or endogenous Trak1, suggesting that the localization of Trak1 to mitochondria is partially impaired by hypertonia-linked Trak1 mutation." (PMID 28924745, 2018). "Our findings uncover a novel function of Trak1 as a regulator of mitochondrial fusion and provide evidence linking dysregulated mitochondrial dynamics to hypertonia pathogenesis." (PMID 28924745, 2018). "By using co-immunoprecipitation analyses, we found that endogenous Trak1 specifically interacted with Mfn1 and Mfn2 but not with Drp1 and that the ability of Trak1 to interact with mitofusins was not affected by hypertonia-associated mutation." (PMID 28924745, 2018). "TRAK1 has been shown to play a role in endosome-to-lysosome trafficking and GABA(A) receptor homeostasis in hypertonia, which is observed in human neurological diseases." (PMID 28388658, 2017).
bladder cancer (2 papers, 2017 to 2019). "We found that the expression levels of DAPK1 and TRAK1 were positively significantly correlated with each other and that a low level expression of TRAK1 was associated with a poorer survival in the three bladder cancer patient cohorts." (PMID 28388658, 2017). "Our results show that TRAK1 expression was significantly associated with both DAPK1 expression and survival consistently in all the three bladder cancer patient cohorts and suggest that TRAK1 is a favourable prognostic marker in bladder cancer." (PMID 28388658, 2017). "Interestingly, TRAK1, by itself, was a favorable prognostic marker in the 3 independent bladder cancer datasets." (PMID 28388658, 2017). "In the present study, we have found that TRAK1 was co-regulated with DAPK1 and was a favorable prognostic marker in bladder cancer." (PMID 28388658, 2017). "Further analysis of the 3 independent bladder cancer datasets have identified ACOX1, UPK2, TRAK1, PLEKHG6 and MT1X genes had their expression significantly correlated with that of DAPK1." (PMID 28388658, 2017). "Knockdown of DAPK1 in bladder cancer T24 cells resulted in downregulation of ACOX1, UPK2 and TRAK1." (PMID 28388658, 2017). "Gaballah identified candidate genes: PURA, SRPK2, TRAK1, BRD2, and UPF3 in progression and invasiveness of bladder carcinoma based on DEGs acquired by comparing invasive and noninvasive samples by Limma R packages in 2016." (PMID 30723390, 2019).
developmental delay (2 papers, 2024 to 2025). "A meta-analysis of TRAK1-associated epilepsy revealed that all patients had varying degrees of developmental disorders, such as developmental delay, microcephaly, central hypotonia, and failure to thrive." (PMID 38410694, 2024).
Encephalopathy (2 papers, 2018 to 2024). Encephalopathy is a term that means brain disease, damage, or malfunction. "Recessive TRAK1 variants have been associated with DEE68, which is characterized by neurodevelopmental delay, seizures, and fatal encephalopathy." (PMID 38410694, 2024).
neuroblastoma (2 papers, 2014 to 2024). Neuroblastoma (NB) is the most common solid, extracranial childhood tumor. "FLAG-TRAK1 also co-immunoprecipitates endogenous 100 kDa full-length DISC1 from the human embryonic kidney cell line HEK293, while endogenous TRAK1 co-immunoprecipitates endogenous 100 kDa DISC1 from HEK293 cells and the human neuroblastoma cell line SH-SY5Y." (PMID 24092329, 2014).
schizophrenia (2 papers, 2016 to 2022). A major psychotic disorder characterized by abnormalities in the perception or expression of reality. "Additionally, one predicted pathogenic mutation in TRAK1 has also been described in the literature in a subject with schizophrenia." (PMID 35205252, 2022). "Although none of the genes was previously implicated in ASD, one, TRAK1 [chr3:42,244,127 (hg19), A > G], interacts with the known schizophrenia gene DISC1, and one other gene, CLSTN3 [chr12:7310,284 (hg19), G > A], was deemed likely to be pathogenic according to the ACMG guidelines." (PMID 35205252, 2022). "Here we demonstrate that the schizophrenia-associated protein, DISC1, interacts with Miro1 and Miro2 as well as TRAK1 and TRAK2 to affect axonal and dendritic transport of mitochondria." (PMID 26553875, 2016). "TRAK1 is closely associated with DISC1, itself implicated in schizophrenia and neural development." (PMID 35205252, 2022).
breast carcinoma (1 paper, 2018). "In MDA-MB-231 cells, TRAK1 knockdown inhibited, whereas TRAK2 knockdown promoted mitochondrial distribution, showing that their preferential roles in breast cancer cells are anterograde and retrograde trafficking of mitochondria, respectively." (PMID 29992963, 2018). "Protein expression levels of TRAK1 and TRAK2 were significantly high in breast cancer cells with high (H) invasiveness, compared to those with low (L) invasiveness." (PMID 29992963, 2018).
colorectal adenoma (1 paper, 2011). An adenoma that arises from the colon or rectum. "Alternative TSS usage in colorectal adenoma and cancer samples has been shown for nine genes, and OSBPL1A and TRAK1 were found to be regulated in vitro by Wnt signaling." (PMID 21999571, 2011).
epilepsy (1 paper, 2024). A brain disorder characterized by episodes of abnormally increased neuronal discharge resulting in transient episodes of sensory or motor neurological dysfunction, or psychic dysfunction. "Our study emphasizes the diagnostic and prognostic importance of detecting TRAK1 variant expression in patients with epilepsy." (PMID 38410694, 2024). "Detailed neurological phenotypes of all patients with epilepsy having TRAK1 variants were analyzed to assess the genotype–phenotype correlations." (PMID 38410694, 2024). "Our study highlights the diagnostic and prognostic importance of detecting TRAK1 variant expression in patients with epilepsy." (PMID 38410694, 2024). "We identified biallelic TRAK1 variants in patients with epilepsy and developmental disorders, who experienced seizures that progressed to status epilepticus." (PMID 38410694, 2024). "We assessed the correlation between TRAK1 variants and epilepsy and further analyzed the genotype–phenotype relationships in TRAK1-associated epilepsy based on this and previous cases." (PMID 38410694, 2024). "We identified a novel, rare compound heterozygous TRAK1 variant in a pediatric patient with epilepsy and a mild developmental disorder." (PMID 38410694, 2024). "Further results for six variants in 12 patients with epilepsy indicated that biallelic TRAK1 variants (including homozygous or compound heterozygous variants) were associated with epilepsy with developmental disorders." (PMID 38410694, 2024). "To evaluate the relationship between TRAK1 variants and epilepsy, we summarized and analyzed relevant cases, including neurological phenotypes." (PMID 38410694, 2024). "In this study, patients with epilepsy carried biallelic TRAK1 variants." (PMID 38410694, 2024). "The findings further show that compound heterozygous TRAK1 variants are associated with epilepsy." (PMID 38410694, 2024). "The aim of this study was to investigate the genotype–phenotype of TRAK1-associated epilepsy." (PMID 38410694, 2024). "Biallelic TRAK1 variants can cause epilepsy and developmental disorders." (PMID 38410694, 2024).
Epileptic spasm (1 paper, 2024). A sudden flexion, extension, or mixed extension-flexion of predominantly proximal and truncal muscles that is usually more sustained than a myoclonic movement but not as sustained as a tonic seizure. "We identified one patient with the TRAK1 compound heterozygous variant who was characterized by early infantile epileptic spasms and developmental disorders." (PMID 38410694, 2024). "In the present study, biallelic TRAK1 missense variants were identified in a pediatric patient with epileptic spasms and developmental disorders." (PMID 38410694, 2024).
Intellectual disability (1 paper, 2022). "Although none of the genes habouring predicted-damaging PZMs was previously implicated in ASD, intellectual disability (ID), or other neurodevelopmental disorders, two, TRAK1 and CLSTN3, are widely expressed in the brain." (PMID 35205252, 2022).
lymphoma (1 paper, 2018). A malignant (clonal) proliferation of B- lymphocytes or T- lymphocytes which involves the lymph nodes, bone marrow and/or extranodal sites. "LNP1—together with other highly mutated genes, such as FADS6 and TRAK1—was firstly found in this lymphoma, and was verified by Sanger sequencing." (PMID 30106962, 2018).
migraine (1 paper, 2021). "We identified common targets associated with migraine and the hsa‐miR‐155‐5p high confidence target space such as PLP1, TRAK1, SYNJ1, and CREB5." (PMID 34486248, 2021).
multiple myeloma (1 paper, 2016). "One of these included the enhancer located a-DMR in the TRAK1 locus associated with the late onset neoplasm, multiple myeloma (rs1052501)." (PMID 27663977, 2016).
osteoarthritis (1 paper, 2023). A noninflammatory degenerative joint disease occurring chiefly in older persons, characterized by degeneration of the articular cartilage, hypertrophy of bone at the margins and changes in the synovial membrane. "Alternatively, six of the top concordant genes (HTR7, TRAK1, LAMA4, HS6ST1, PDE4A, GPNMB) at 52 weeks have been documented in prior osteoarthritis literature." (PMID 37134114, 2023).
status epilepticus (1 paper, 2024). Status epilepticus is defined as a continuous seizure lasting more than 30 min, or two or more seizures without full recovery of consciousness between any of them. "Knockdown of TRAK1 in CA1 neurons shortened the time from the first episode to status epilepticus and increased the frequency of epileptic seizures." (PMID 38410694, 2024).
temporal lobe epilepsy (1 paper, 2023). A localization-related (focal) form of epilepsy characterized by recurrent seizures that arise from foci within the temporal lobe, most commonly from its mesial aspect. "For example, the expression of mitochondrial trafficking kinesin protein 1 (TRAK1) is decreased in temporal lobe epilepsy, and silencing of TRAK1 increases susceptibility to seizures." (PMID 36734302, 2023).
cancer (7 papers, 2011 to 2022). A tumor composed of atypical neoplastic, often pleomorphic cells that invade other tissues. "Moreover, elevated Trak1 protein expression is associated with several types of cancers and variants in Trak1 are linked to childhood absence epilepsy in humans." (PMID 28924745, 2018). "In summary, the experiments confirmed that the tumor associated alternative TSS usages observed for TCF12, OSBPL1A and TRAK1 were indeed due to altered expression in the carcinoma cells, and not a consequence of altered tissue composition." (PMID 21999571, 2011). "In addition, TRAK1, the ortholog of TRAK2, has been identified as MGb2-Ag—a novel cancer biomarker." (PMID 31242667, 2019).
neurodevelopmental disorder (2 papers, 2022 to 2025). A behavioral and cognitive disorder with onset during the developmental period that involves impaired or aberrant development of intellectual, motor, or social functions. "Although previously associated with neurodevelopmental disorders, TRAK1 is not currently listed in the SFARI database." (PMID 40558542, 2025).
tumor (2 papers, 2011 to 2022). "Finally, Trafficking kinesin-binding protein 1 (TRAK1), a kinesin-binding protein associated with mitochondria, contains two alternative start exons (exon 1A and 1B) with differential expression in normal and tumor samples." (PMID 21999571, 2011). "The predominantly metastatic tumours in our cohort contained more frequent mutations in several genes such as SETD2, APC, KDM5C, HIF1A, RBM10, TRAK1 and FBXW7, while we detected lower mutation rates in VHL compared to the primary tumours analysed in the TCGA study." (PMID 35231161, 2022). "TRAK1 and EGFR mutations were present in 9 and 6 tumours from 7 and 4 patients, respectively." (PMID 35231161, 2022). "Notably, significant functional differences are predicted between the long or short isoforms of TCF12, OSBPL1A, TRAK1, CHEK1, ANK3, LMO7 and SCIN indicating that the observed tumor associated changes in TSS usage probably have an impact on the growth properties of the neoplastic cells." (PMID 21999571, 2011). "TRAK1 exon 1A was found to be expressed in only two normal epithelial samples, whereas no expression of the tumor preferred exon 1B was observed in either fraction from the normal sample." (PMID 21999571, 2011).
neurodegenerative disease (1 paper, 2018). A disorder of the central nervous system characterized by gradual and progressive loss of neural tissue and neurologic function. "Based on our results, we suggest that enhancement of Trak1-mediated mitochondrial fusion could represent a novel therapeutic strategy to combat mitochondrial fragmentation in a number of neurodegenerative diseases." (PMID 28924745, 2018).
TRAK1 also shares sentences with these, for which no sentence is quoted: Neurodevelopmental delay (2 papers); adenoma (1); autism (1); ciliopathies (1); Failure to thrive (1); gastric cancer (1); Klinefelter syndrome (1); leukemia (1); microcephaly (1); neurological diseases (1); sarcoidosis (1).